ANGPTL8 (angiopoietin like 8)
Diseases named in the same sentence as ANGPTL8 in open-access papers (continued):
Sharing a sentence is not in itself a finding about the gene and the disease.
Insulin resistance (continued). "At baseline, ANGPTL8 concentrations were positively associated with triglycerides (TG) (r = 0.168, P = 0.010), whereas ANGPTL3 levels were associated with fasting insulin (r = 0.248, P < 0.001) and the homeostasis model assessment of insulin resistance (HOMA-IR) (r = 0.197, P = 0.002)." (PMID 26739706, 2016). "For instance, TDAG51 modulates the SREBP-1/ANGPTL8 pathway in GDM to relieve the damaged lipid metabolism and insulin resistance." (PMID 40877960, 2025). "That is to say, insulin acts on insulin receptor to activate PI3K/Akt pathway, and then the expression of ANGPTL8 increases; in insulin resistance, PI3K/Akt pathway was damaged and ANGPTL8 expression was downregulated." (PMID 34582711, 2021). "Noteworthy, previous studies described higher ANGPTL8 mRNA expression in omental fat from individuals affected by obesity with NAFLD and insulin resistance as compared with controls matched for BMI with a normal insulin sensitivity." (PMID 33067796, 2021). "In the insulin resistance model of L02 hepatocytes induced by various factors (such as palmitic acid, dexamethasone, TNF-α, IL-1β and insulin), the expression of ANGPTL8 increased only in the presence of hyperinsulinaemia." (PMID 34582711, 2021). "This study aims to investigate the effect of angiopoietin like 8 (ANGPTL8) on gestational diabetes mellitus (GDM) and insulin resistance (IR)." (PMID 34163433, 2021). "Numerous studies have demonstrated that ANGPTL8 levels are positively correlated with FPG and insulin resistance." (PMID 32034642, 2020). "And one research declared that ANGPTL8 levels are reduced in full-blown PCOS patients and positively associated with low-density lipoprotein cholesterol; therefore, further research is needed to elucidate the role of ANGPTL8 in PCOS and insulin resistance." (PMID 31346314, 2019). "Taken together, ANGPTL8 levels increased with the level of FPG and increased with the level of fasting C-peptide because of insulin resistance." (PMID 29082263, 2017). "Furthermore, the relationship between ANGPTL8 and NAFLD appears to weaken when adjusted for insulin resistance, suggesting a mediating role of the latter." (PMID 40276549, 2025). "ANGPTL-8 levels were lower in patients with acromegaly with NAFLD, suggesting that high levels represent a reaction to insulin resistance rather than being a cause of NAFLD." (PMID 37590020, 2023). "Serum ANGPTL8 levels were increased in patients with type 2 diabetes mellitus (T2DM), positively correlated with FPG (fasting plasma glucose) and fasting C-peptide and negatively correlated with insulin resistance." (PMID 35851270, 2022). "Although the earliest study observed that the expression of ANGPTL8 increased in the state of insulin resistance, with the progress of follow-up studies, people realized that insulin, rather than insulin resistance, promoted the expression of ANGPTL8." (PMID 34582711, 2021). "Our data shows that in subjects with morbid obesity and insulin resistance, there are not significant changes in the plasma levels of ANGPTL8 in relation to non-obese patients." (PMID 32069954, 2020). "ANGPTL8 is related to two important processes leading to the development of T2DM, insulin resistance, and lipid metabolism and can regulate β-cell replication in insulin resistance." (PMID 33343659, 2020). "We have observed a negative correlation between the ANGPTL8, insulin and homeostasis model assessment of insulin resistance (HOMA-IR)." (PMID 32069954, 2020). "It has also been suggested that Angptl8 is positively correlated with hepatocellular lipid content, independent of obesity and insulin resistance." (PMID 31380419, 2019). "Furthermore, some studies have reported a positive relationship between blood glucose, homeostasis model assessment of insulin resistance (HOMA-IR) and ANGPTL8 in type 2 diabetic patients." (PMID 30072957, 2018).
Insulin resistance (continued). "The mediating roles of hyperglycemia and insulin resistance in the relationship between ANGPTL8 and ACR were not evaluated because of these nonsignificant associations." (PMID 30072957, 2018). "Because fasting plasma glucose, HbA1c and HOMA-IR were not related to ANGPTL8 significantly, the mediator roles of hyperglycemia and insulin resistance in the relationship between ANGPTL8 and c-IMT were not further evaluated." (PMID 30007407, 2018). "Lower ANGPTL-8 in patients with acromegaly and NAFLD implies this hormone may be raised because of insulin resistance rather than being a cause for NAFLD." (PMID 37590020, 2023). "Mice lacking ANGPTL8 demonstrated typical glucose metabolism in the presence of insulin resistance." (PMID 37679750, 2023). "Compared to conditions of absent metabolic dysregulation and systemic inflammation, values of circulating betatrophin/ANGPTL8 were significantly increased in sepsis and non-significantly increased in the insulin resistance group (p = 0.009 and p = 0.053, respectively)." (PMID 36551906, 2022). "However, our studies seem to indicate that ANGPTL8 could be not responsible for the insulin resistance, which consistent with other different view." (PMID 34603198, 2021). "An interesting observation in present study was that, unlike other studies, ANGPTL8 correlated directly and significantly with hs-CRP, but not with homeostatic model assessment insulin resistance (HOMA-IR), where there was no such significant correlation." (PMID 34603198, 2021). "Third, TG partially mediated this positive relationship between ANGPTL8 and c-IMT, whereas insulin resistance and hyperglycemia did not play a mediating role in this relationship." (PMID 30007407, 2018).
metabolic syndrome (53 papers, 2014 to 2025). A cluster of metabolic risk factors for CARDIOVASCULAR DISEASES and TYPE 2 DIABETES MELLITUS. "ANGPTL8, which is expressed and secreted mainly by liver and adipose tissue, is closely associated with metabolic syndrome." (PMID 39019343, 2024). "The same ANGPTL8 protein that most likely prevented hunger in the ancestors of humans now predisposes people to metabolic syndrome." (PMID 39274442, 2024). "On the other hand, studies have also reported increased circulating levels of ANGPTL3, ANGPTL4 or ANGPTL8 in association with metabolic syndrome in cohorts with obesity, diabetes and/or dyslipidemia." (PMID 38879166, 2024). "ANGPTL8 showed a strong positive correlation with hsCRP, leptin, and chemerin which are well-known risk factors specifically for obesity, and broadly for metabolic syndrome." (PMID 38189043, 2023). "The results of clinical prospective study also showed that the baseline ANGPTL8 level was negatively correlated with the risk of metabolic syndrome, even after multivariable adjustment." (PMID 34582711, 2021). "It was reported that ANGPTL8 levels are positively associated with obesity, diabetes, and dyslipidemia." (PMID 34959891, 2021). "Related clinical studies have shown that serum ANGPTL8 is associated with diabetes and metabolic syndrome, as well as chronic complications related to diabetes, including diabetic nephropathy and diabetic retinopathy." (PMID 33343659, 2020). "Ironically, in a world of caloric abundance, the same ANGPTL8 protein that likely protected our ancestors from starvation now predisposes us to metabolic syndrome." (PMID 32487544, 2020). "We recently illustrated that angiopoietin-like protein 8 (ANGPTL8), also known as betatrophin, is strongly associated with high sensitivity C-reactive protein (HsCRP) levels and an increased incidence of metabolic syndrome." (PMID 29490644, 2018). "Association between circulating ANGPTL8 levels and laboratory tests relevant to obesity, impaired glycometabolism, or dyslipidemia (n = 800)." (PMID 29538435, 2018). "Furthermore, several studies showed ANGPTL8 associations with metabolic syndrome, dyslipidemia, and metabolic-associated fatty liver disease." (PMID 40725697, 2025). "The collective involvement of Ang proteins and ANGPTL8 in vascular biology and metabolic equilibrium renders them highly promising targets for diagnostic and therapeutic interventions in conditions such as metabolic syndromes and cardiovascular disorders." (PMID 38790911, 2024). "Our findings suggest ANGPTL8, particularly interacting with leptin, might have a protective role in cardiac remodeling among youths with risk for metabolic syndrome." (PMID 35145478, 2021). "Indeed, earlier research assessing the relationship between ANGPTL8 and the risk of metabolic syndrome in adults indicated that ANGPTL8 was a good predictor of increased TG in females but not in males." (PMID 34959891, 2021). "Although Angptl8 expression has been strongly linked to the onset of metabolic syndrome, the molecular regulation of Angptl8 is largely unknown." (PMID 31470507, 2019). "A recent study has suggested the involvement of angiopoietin-like protein 8 (ANGPTL8) in the association between dyslipidemia and arteriosclerosis, indicating that hypertriglyceridemia is partially involved in the association between ANGPTL8 and arteriosclerosis." (PMID 30898163, 2019). "As the deregulation of several transcription factors, cytokine, and enzymes in liver is the hallmark of metabolic syndrome, we hypothesized that Angptl8 could be regulated by liver-derived and metabolism-related factors." (PMID 31470507, 2019). "However, the role of ANGPTL8 in metabolic syndrome as well as its association with inflammatory markers like HsCRP has not yet been well studied." (PMID 26850725, 2016). "High concentrations of ANGPTL8 may decrease the risk of atherogenic dyslipidemia in psoriatics." (PMID 36983346, 2023).
metabolic syndrome (continued). "Elevated ANGPTL8 levels have been found to correlate with fasting glucose, triglycerides, obesity, and metabolic syndrome." (PMID 40137149, 2025). "For example, we have shown that levels of ANGPTL8 were significantly elevated in adult individuals afflicted with obesity, diabetes, and metabolic syndrome compared with healthy control individuals." (PMID 38189043, 2023). "Significantly, the levels of ANGPTL8 in the bloodstream are lower in various metabolic disorders, such as obesity, type 2 diabetes (T2D), and dyslipidemia." (PMID 37679750, 2023). "We further demonstrated that the level of circulating ANGPTL8 in people with metabolic syndrome is positively correlated with levels of hsCRP, implicating ANGPTL8 in metabolic and inflammatory pathways." (PMID 37755252, 2023). "Despite comparable betatrophin/ANGPTL8 mRNA expression in AT (p = 0.24), we found significantly increased circulating betatrophin/ANGPTL8 with septic dyslipidemia (p = 0.009)." (PMID 36551906, 2022). "Another example of the use of ASOs in the setting of metabolic syndrome is the targeting of angiopoietin-like 8 (ANGPTL8)." (PMID 35295579, 2022). "We provide the first evidence on the regulation of betatrophin/ANGPTL8 under conditions of septic dyslipidemia." (PMID 36551906, 2022). "Targeting ANGPTL3 or ANGPTL8 represents promising strategies for the development of new treatment of dyslipidemia." (PMID 34356847, 2021). "Angiopoietin-like protein 8 (ANGPTL8) is an hepatokine altered in several metabolic conditions, such as obesity, type 2 diabetes, dyslipidemia and nonalcoholic fatty liver disease (NAFLD)." (PMID 34884755, 2021). "Recently, targeting ANGPTL3 and ANGPTL8 to lower circulating TGs levels in the treatment of dyslipidemia is also pursued." (PMID 34356847, 2021). "To access the regulation of Angptl8 in metabolic syndrome, we first established a HFD-induced obese mouse model." (PMID 31470507, 2019). "The relationship between ANGPTL8 and biomarkers of renal function was also observed in studies focusing on dyslipidemia and MS." (PMID 29719529, 2018). "Different researches have shown that ANGPTL8 concentrations were altered in diseases such as obesity, diabetes mellitus, metabolic syndrome and non-alcoholic fatty liver disease (NAFLD)." (PMID 30021607, 2018). "In obese subjects with the metabolic syndrome prescribed to hypocaloric diets, ANGPTL8 level was inversely correlated with protein intake, particularly with animal-derived protein intake." (PMID 29719529, 2018). "Recent studies have confirmed a link between circulating levels of ANGPTL8 and cardiovascular disease related biomarkers such as metabolic syndrome and inflammatory cytokines." (PMID 30007407, 2018). "Circulating ANGPTL8 levels were relatively high in the aging and in males, the obese, and in dyslipidemia, while ANGPTL8 concentration was relatively low in conditions of impaired glycometabolism." (PMID 29538435, 2018). "A previous study showed that ANGPTL8 was increased in metabolic syndrome patients and presented a strongly positive correlation with hsCRP, implying a potential role of ANGPTL8 in inflammation." (PMID 30409151, 2018). "As a result ANGPTL8 has been suggested as a potential therapeutic target for dyslipidemia and diabetes." (PMID 26784326, 2016). "Considering the high prevalence of dyslipidemia in diabetics including patients with T1D, it is of interest to determine how ANGPTL8 affects glucose homeostasis and serum lipid profiles in T1D models." (PMID 31741751, 2016). "After 3.5-year follow-up, we observed an inverse correlation between the baseline ANGPTL8/betatrophin levels and the incidence of metabolic syndrome, even after multivariate adjustments." (PMID 27345212, 2016). "By suppressing ANGPTL8, it may be feasible to reverse thrifty features such as obesity, circulating TG levels, and metabolic syndrome." (PMID 38303975, 2023).
metabolic syndrome (continued). "ANGPTL8 is closely associated with metabolic disorder-related diseases, such as type 2 diabetes mellitus (T2DM), nonalcoholic fatty liver disease (NAFLD), obesity and metabolic syndrome." (PMID 38107478, 2023). "Based on our study, it appears that elevated levels of ANGPTL8 may reduce the likelihood of atherogenic dyslipidemia in individuals with psoriasis, and treatment for psoriasis may impact the protective effects of ANGPTL8." (PMID 36983346, 2023). "The cytokine betatrophin/Angiopoietin-like protein 8 (ANGPTL8) plays a role in the regulation of triacylglyceride metabolism, though its function in septic dyslipidemia remains unknown." (PMID 36551906, 2022). "Interestingly, serum ANGPTL8 concentrations are decreased in several metabolic conditions, such as obesity, T2D or dyslipidemia and increase after bariatric surgery, although contradictory results have been published." (PMID 34884755, 2021). "Angiopoietin-like protein 8 (ANGPTL8) is associated with reduced HDL-cholesterol levels and may contribute to the development of dyslipidemia." (PMID 33953838, 2021). "On the whole, an improved lipid profile and lower risk of CAD in ANGPTL8 PTV carriers compared to noncarriers lends support to the efficacy of an antibody-based inhibition of ANGPTL8 in treating dyslipidemia and CAD." (PMID 33909604, 2021). "Recent studies revealed an association between ANGPTL3 and ANGPTL8 with lipid biomarkers in adults, young obese non-diabetic men, children, and adolescents with obesity and metabolic syndrome." (PMID 34959891, 2021). "Knowing these data, we assumed that the increase or decrease of levels of ANGPTL8 in psoriatic patients and all subjects with metabolic syndrome could occur." (PMID 32537470, 2020). "So, there is a possibility that pathological reactions involved in the pathogenesis of psoriasis might influence the expression of ANGPTL8 more than those involved in metabolic syndrome." (PMID 32537470, 2020). "Our data suggested that the GNMT may function as a negative regulator for Angptl8 expression in metabolic syndrome." (PMID 31470507, 2019). "In conclusion, our study suggests that downregulation of hepatic GNMT and upregulation of hepatic and circulating Angptl8 may be a potential biomarker for HFD-induced metabolic syndrome." (PMID 31470507, 2019). "In the current study, we investigated circulating full-length ANGPTL8 concentrations in patients with dyslipidemia and the association between full-length ANGPTL8 concentrations and serum lipids in Chinese people without diabetes." (PMID 30021605, 2018). "Since renal dysfunction influenced lipid metabolism, the relationship between ANGPTL8 and dyslipidemia might be confounded by the degree of proteinuria." (PMID 29719529, 2018). "Therefore, ANGPTL8 has been suggested as a potential therapeutic target for dyslipidemia and inhibition of ANGPTL8 has been highlighted as a novel therapeutic strategy for reducing plasma lipoprotein levels." (PMID 29973202, 2018). "By contrast, circulating ANGPTL8 levels were positively associated with increased levels of LDL-cholesterol and TG and with decreased levels of HDL-cholesterol in the category of dyslipidemia, in addition to a positive association with obesity, as estimated by BMI." (PMID 29538435, 2018). "In people without diabetes, circulating full-length ANGPTL8 concentrations in patients with dyslipidemia were significantly elevated compared with non-dyslipidemia, and ANGPTL8 was positively associated with serum non-HDL-C levels." (PMID 30021605, 2018). "We also found that patients with dyslipidemia in the current study exhibited a dramatic increase in circulating full-length ANGPTL8 concentrations, circulating full-length ANGPTL8 concentrations were positively associated with serum TG and TC levels and negatively associated with HDL-C levels." (PMID 30021605, 2018).